UBXN1 (UBX domain protein 1)
Description:
Ubiquitin-binding protein that plays a role in the modulation of innate immune response. Blocks both the RIG-I-like receptors (RLR) and NF-kappa-B pathways. Following viral infection, UBXN1 is induced and recruited to the RLR component MAVS. In turn, interferes with MAVS oligomerization, and disrupts the MAVS/TRAF3/TRAF6 signalosome. This function probably serves as a brake to prevent excessive RLR signaling. Interferes with the TNFalpha-triggered NF-kappa-B pathway by interacting with cellular inhibitors of apoptosis proteins (cIAPs) and thereby inhibiting their recruitment to TNFR1. Also prevents the activation of NF-kappa-B by associating with CUL1 and thus inhibiting NF-kappa-B inhibitor alpha/NFKBIA degradation that remains bound to NF-kappa-B. Interacts with the BRCA1-BARD1 heterodimer and regulates its activity. Specifically binds 'Lys-6'-linked polyubiquitin chains. Interaction with autoubiquitinated BRCA1 leads to the inhibition of the E3 ubiquitin-protein ligase activity of the BRCA1-BARD1 heterodimer. Component of a complex required to couple deglycosylation and proteasome-mediated degradation of misfolded proteins in the endoplasmic reticulum that are retrotranslocated in the cytosol.
Synonyms: SAKS1; LOC51035; 2B28; UBXD10
Tractability: PROTAC: ubiquitination databases record sites on it; its protein half-life has been measured.
Gene: Protein-coding gene on chromosome 11 (62,676,498 to 62,679,332, reverse strand). Ensembl gene ENSG00000162191.
Subcellular location: Cytoplasm
Subcellular location (Human Protein Atlas): Cytosol; Nucleoplasm
Pathways (Reactome):
DNA Repair: Recruitment and ATM-mediated phosphorylation of repair and signaling proteins at DNA double strand breaks
Metabolism of proteins: N-glycan trimming in the ER and Calnexin/Calreticulin cycle
Gene Ontology:
Molecular function: ATPase binding; K48-linked polyubiquitin modification-dependent protein binding; K6-linked polyubiquitin modification-dependent protein binding; polyubiquitin modification-dependent protein binding; proteasome regulatory particle binding; protein binding; ubiquitin binding; ubiquitin protein ligase binding
Biological process: negative regulation of ERAD pathway; negative regulation of proteasomal ubiquitin-dependent protein catabolic process; negative regulation of protein K48-linked deubiquitination; negative regulation of protein ubiquitination; proteasome-mediated ubiquitin-dependent protein catabolic process; ubiquitin-dependent protein catabolic process
Cellular component: cytoplasm; cytosol; endoplasmic reticulum; VCP-NPL4-UFD1 AAA ATPase complex; ATPase complex; nucleoplasm
Genetic constraint (gnomAD): Loss-of-function variants: 21 observed, 41.62 expected, observed/expected ratio (o/e) 0.5, 90% interval 0.36 to 0.73. The upper end of that interval is the gene's LOEUF score, 0.73, which puts it in group 2 of 6, group 1 being the genes least tolerant of losing a copy. Missense variants: 374 observed, 397.08 expected, observed/expected ratio (o/e) 0.94, 90% interval 0.87 to 1.03. Synonymous variants: 172 observed, 149.63 expected, observed/expected ratio (o/e) 1.15, 90% interval 1.01 to 1.3.
Homologues: Orthologues: macaque UBXN1 (99% identical), chimpanzee UBXN1 (95% identical), rabbit UBXN1 (95% identical), mouse Ubxn1 (93% identical), rat Ubxn1 (93% identical), pig UBXN1 (91% identical), dog UBXN1 (89% identical), guinea pig UBXN1 (86% identical), tropical clawed frog ubxn1 (64% identical), zebrafish ubxn1 (52% identical), Drosophila melanogaster CG8209 (42% identical), Caenorhabditis elegans ubxn-1 (31% identical). Paralogues in human: TNRC6C (30% identical), TNRC6B (26% identical), TNRC6A (26% identical), UBXN4 (18% identical), UBAC1 (11% identical).
Diseases named in the same sentence as UBXN1 in open-access papers:
UBXN1 is named in the same sentence as 17 diseases in open-access papers, as found by Europe PMC text mining. Sharing a sentence is not in itself a finding about the gene and the disease. The quoted sentences say what the papers report.
glioma (6 papers, 2021 to 2024). A benign or malignant brain and spinal cord tumor that arises from glial cells (astrocytes, oligodendrocytes, ependymal cells). "Recent studies have demonstrated that the expression of UBXN1 is heterogeneous across tumors but generally decreased in gliomas." (PMID 38773518, 2024). "YTHDF2 recognizes METTL3-mediated m6A on UBXN1 mRNA and decreases its expression, which in turn promotes NF-κB signaling and the malignant progression of gliomas." (PMID 38773518, 2024). "Our findings confirmed that YTHDF2 promotes the malignant progression of gliomas and revealed important insight into the upstream regulatory mechanism of NF-κB activation via UBXN1 with a primary focus on m6A modification." (PMID 34246306, 2021). "Together, these findings showed that YTHDF2 can accelerate UBXN1 mRNA decay in gliomas via METTL3-mediated m6A modification." (PMID 34246306, 2021). "We also observed that UBXN1 mRNA levels were significantly stratified with the prognosis of glioma cases with high YTHDF2 expression (higher than the median value) in several datasets." (PMID 34246306, 2021). "Mechanistically, YTHDF2 accelerates UBXN1 mRNA decay in gliomas by recognizing the m6A modification mediated by METTL3." (PMID 34246306, 2021). "Knockdown and overexpression were used to evaluate the effects of YTHDF2, methyltransferase-like 3 (METTL3), and UBX domain protein 1 (UBXN1) on glioma malignancy in cell and orthotopic xenograft models." (PMID 34246306, 2021). "To further validate the role of UBXN1 in YTHDF2 promotion of glioma progression and NF-κB activation, we overexpressed UBXN1 in cells overexpressing YTHDF2." (PMID 34246306, 2021). "Together, these data indicate that there are METTL3-mediated m6A modification sites on UBXN1 mRNA that have the potential to be recognized by YTHDF2 in glioma cells." (PMID 34246306, 2021). "Additionally, we identified UBXN1 as a prognostic factor for better survival of glioma patients with high YTHDF2 expression." (PMID 34246306, 2021). "Collectively, these experiments supported the notion that HOTAIR silencing the expression of UBXN1 can regulate the activation of NF-kB pathway and induce the expression of checkpoint protein PD-L1 on surface of glioma cells, thereby initiating glioma to escape T cell recognition and killing." (PMID 34887871, 2021). "To explore whether there are m6A modification sites on UBXN1 mRNA that have the potential to be recognized by YTHDF2 in glioma cells, we performed MeRIP sequencing in GBM patient-derived N33 cells." (PMID 34246306, 2021). "For example, YTHDF2 promotes glioma malignancy by degrading UBXN1 mRNA, while METTL3-mediated m6A modification enhances glioma metastasis by stabilizing PCBP2." (PMID 38171932, 2023). "To further validate the existence of m6A modification on UBXN1 mRNA in gliomas, we performed MeRIP-sequencing of U87 cells with or without METTL3 knockdown." (PMID 34246306, 2021).
glioblastoma (5 papers, 2022 to 2025). The most malignant astrocytic tumor (WHO grade IV). "For example, lncRNA PRADX activates the NF‐κB pathway by inhibiting UBXN1 expression, thereby promoting the occurrence of glioblastoma and colon adenocarcinoma." (PMID 40095756, 2025). "In another study, YTHDF2 was found to increase UBX domain protein 1 (UBXN1) mRNA degradation in glioblastoma cells." (PMID 38398118, 2024). "YTHDF2 and PRADX decrease UBXN1 expression at the posttranscriptional level and thereby facilitate NF-κB signaling activity in glioblastoma and colon adenocarcinoma progression." (PMID 38773518, 2024). "The lncRNA PRADX peroxiredoxin 1 (PRADX) promotes the nuclear factor-κB (NF-κB) activity via the UBX domain protein 1 (UBXN1) suppression, inducing the tumorigenesis of glioblastoma and colon adenocarcinoma by interacting with the enhancer of zeste homolog 2 (EZH2)." (PMID 35954243, 2022).
prostate carcinoma (3 papers, 2021 to 2024). A carcinoma that arises from epithelial cells of the prostate gland. "In contrast, the inhibition of UBXN1 attenuated prostate cancer cell proliferation by inducing mitochondria-associated apoptosis." (PMID 38773518, 2024). "In this study, we found that germline variants of ARRDC4 and UBXN1 could affect the prostate cancer Gleason score, which could be a potential marker to select aggressive PCa." (PMID 34680357, 2021). "In contrast, UBXN1 promotes AKT signaling and cell proliferation, migration and invasion in prostate cancer cells." (PMID 38773518, 2024). "While depletion of UBXN1 might be profitable for cancer cell survival and proliferation through protecting against endoplasmic reticulum (ER) stress, its up-regulation might facilitate migration and invasion of the cancer cells within the thyroid tissue, as reported in prostate cancer." (PMID 38790250, 2024). "siRNAs targeting UBXN1 and ARRDC4 were used to knockdown the expression of these genes in prostate cancer cells." (PMID 34680357, 2021). "Therefore, to further analyze the possible mechanism of UBXN1 and ARRDC4 in invasion, apoptosis and EMT of prostate cancer cells, Western blotting was used to characterize the protein levels of p-PI3K, PI3K, p-Akt, Akt, and NF-κB." (PMID 34680357, 2021).
viral infection (3 papers, 2018 to 2025). "The expression of UBXN1 is strongly upregulated late during viral infection and it competes with TRAF3/TRAF6 for binding to MAVS (amino acids 455–460), thus blocking MAVS signaling." (PMID 32536927, 2020). "UBXN1 is reportedly induced in a late step of viral infection, and binds to MAVS, and this binding downregulates the induction of IFN by disrupting the MAVS–TRAF3/6 signaling complex in RIG-I-like receptor signaling." (PMID 29769705, 2018). "Our results indicate that NiV V interacts with the C-terminal UBX domain of UBXN1 to stabilize it, suggesting that NiV V potentially enhances the negative regulation of RIG-I-like receptor signaling by stabilizing the induced UBXN1 during viral infection." (PMID 29769705, 2018).
acute myeloid leukaemia (1 paper, 2024). "On the epigenetic front, UBXN1 undergoes silencing through promoter region methylation mediated by the RUNX8-RUNX1T1 fusion protein, resulting in significant inhibition of acute myeloid leukaemia (AML) proliferation." (PMID 38365777, 2024).
Autoimmunity (1 paper, 2017). The occurrence of an immune reaction against the organism's own cells or tissues. "It is possible that enhancement of UBXN1 function could ameliorate inflammatory disorders, certain forms of autoimmunity, and malignancy in which either the RLR or NFκB pathway has been activated." (PMID 28152074, 2017).
breast carcinoma (1 paper, 2024). "Furthermore, UBXN1 recognizes and binds to autoubiquitinated BRCA1, a tumor suppressor for breast cancer, and inhibits its enzymatic function, suggesting that UBXN1 plays an oncogenic role in cancer." (PMID 38773518, 2024).
hepatocellular carcinoma (1 paper, 2024). A malignant tumor that arises from hepatocytes. "Liver hepatocellular carcinoma (LIHC) datasets and HCC patient samples were used to assess the expression of UBXN1." (PMID 38773518, 2024).
malignant glioma (1 paper, 2022). A grade III or grade IV glioma arising from the central nervous system. "METTL3 regulates MGMT, ANPG, COL4A1, MALAT1, and UBXN1 expression in an m6A-dependent manner and promotes the progression of malignant glioma." (PMID 35945641, 2022). "The YTHDF protein family regulates LXRA, HIVEP2, MYC, VEGFA, and UBXN1 expression in an m6A-dependent manner and promotes the occurrence, metastasis and drug resistance of malignant gliomas." (PMID 35945641, 2022).
tumor (10 papers, 2021 to 2025). "This included for example for bendamustine EIF3M involved in cell proliferation, cell cycle progression and cell death, SMAD3 involved in epithelial-to-mesenchymal transition, tumor suppressor and metastasis formation, and UBXN1 influencing EGFR signaling." (PMID 41146244, 2025). "Here, we identified UBXN1 as a tumor promoter in HCC via the maintenance of mitochondrial integrity." (PMID 38773518, 2024). "In summary, these data suggest that a functional interaction between PHB and UBXN1 regulates tumor cell survival." (PMID 38773518, 2024). "Taken together, our findings revealed that UBXN1 hyperactivation frequently occurs and is crucial for liver tumorigenesis and that the tumor-promoting function of UBXN1 occurs through the UBXN1-PHB interaction, which regulates mitochondrial homeostasis." (PMID 38773518, 2024). "UBXN1 has diverse and sometimes opposite functions in regulating tumor progression due to differences in its substrates and cancer types." (PMID 38773518, 2024). "Western blot analysis showed that tumor cells overexpressing PRADX had reduced levels of UBXN1, which in turn decreased IκBα levels and increased the nuclear levels of NF-κB and p-NF-κB." (PMID 33754075, 2021). "GBM and COAD tumor tissues presented the low expression of UBXN1, compared with LGG and adjacent tissues of COAD." (PMID 33754075, 2021). "UBXN1 has dual effects on tumor growth in different types of cancer." (PMID 38773518, 2024). "Within the UBXDF, UBXN1 expression was the highest in tumours." (PMID 38365777, 2024). "As expected, knockout of Ubxn1 significantly inhibited tumor development in these two sets of autochthonous liver tumor models, as evidenced by a decreased liver/weight ratio and increased survival in the Ubxn1-KO (sgUbxn1) group compared with those in the control (sgCon) group." (PMID 38773518, 2024). "The results showed that overexpression of UBXN1 strongly promoted the proliferation potential of tumor cells cultured under serum starvation conditions, and that knockdown of UBXN1 suppressed the proliferation of cultured PLC/PRF/5, MHCC97 H and LPC-HRas cells." (PMID 38773518, 2024). "Next, we investigated whether UBXN1 regulates tumor proliferation in vitro." (PMID 38773518, 2024). "Notably, UBXN1 overexpression markedly attenuated tumor cell apoptosis induced by serum starvation." (PMID 38773518, 2024). "We further used a TUNEL assay to examine tumor cell apoptosis in human HCC xenografts, and the results showed that UBXN1-knockdown greatly increased the number of TUNEL+ cells." (PMID 38773518, 2024). "Mechanistically, YTHDF2 accelerates UBXN1 mRNA degradation by recognizing METTL3-mediated m6A modification sites on UBXN1 mRNA, activating NF-κB and accelerating tumor progression." (PMID 37964279, 2023). "Other downregulated genes, such as HARS, UBXN1, EBAG9 and SGK1, reduce cytotoxic activity of T lymphocytes, block tumor T cell infiltration, drive T helper type 2 differentiation (TH2) or memory differentiation in CD8 T cells when expression is lost." (PMID 34654826, 2021). "Assessment of HCC cell growth in vivo and in vitro, including tumour formation, colony formation, TUNEL and FACS assays, was conducted to determine the effects of UBXN1 on HCC cells, as well as the involvement of the UBXN1-prohibitin (PHB) interaction in mitochondrial function." (PMID 38773518, 2024). "Top underexpressed tumor suppressor candidates such as UBXN1, HNRNPA1, PPP1R15A, and LAPTM5 may also be contributing to tumor tissue formation through inhibition of apoptosis at initial stages of cancerogenesis." (PMID 36359790, 2022). "Interestingly, the ubiquitination gene UBXN1 (UBX domain protein 1), an important negative regulator of the unfolded protein response, was significantly up-regulated in the profiled tumor (x(T) = 1.75), but massively down-regulated in both cell lines (x(Φ) = −41.96, x(Θ) = −106.57)." (PMID 38790250, 2024).
tumor (continued). "Since the intertumor (tumor by tumor) heterogeneity in genetic background or biological context substantially exists in HCC, the compensatory mechanisms consisting of overlapping molecular events or alteration of the surrogates may be present and account for this divergence in UBXN1 expression." (PMID 38773518, 2024).
cancer (7 papers, 2016 to 2025). A tumor composed of atypical neoplastic, often pleomorphic cells that invade other tissues. "UBXN1 is aberrantly expressed in several types of cancer and is implicated in the regulation of multiple biological processes through interactions with the multifunctional AAA-ATPase p97/VCP protein or ubiquitinated proteins via its UBX or UBA domain." (PMID 38773518, 2024). "The rs200944490 (ARRDC4) and rs117555780 (UBXN1) were identified as candidate markers predictive of PCa Gleason score which is strongly associated with cancer aggressiveness." (PMID 34680357, 2021). "This study confirmed for the first time the cancer‐promoting effect of m6A‐modified UBXN1 in cancer." (PMID 40095756, 2025). "UBXN1-dependent inhibition of pro-survival protein cIAP1 and tumor suppressor protein BRCA1 suggests a controversial role for UBXN1 cancer." (PMID 27754413, 2016). "For example, most cancer tissues exhibit weak to moderate cytoplasmic and/or nuclear immunoreactivity in the ASPSCR1, UBXN2A, UBXN10, UBXN1, FAF1, FAF2, UBXD2B proteins." (PMID 38365777, 2024). "Since epithelial-to-mesenchymal transition (EMT) actively relates to the invasion and metastasis of cancer cells, the expression of EMT markers such as vimentin and E-cadherin in PCa cells following knockdown of UBXN1 and ARRDC4 was characterized." (PMID 34680357, 2021). "We identified a novel cancer driver lncRNA, PRADX that recruits PRC2/DDX5 complex by interacting with EZH2 and promotes NF-κB activity via UBXN1 suppression, which in turn contributes to GBM and COAD tumorigenesis." (PMID 33754075, 2021). "Further experiments in cancer as well as immortalized noncancerous cell lines showed that knockdown of UBXN1 potentiates TNFα-triggered NF-κB signaling, suggesting UBXN1 is a physiological suppressor of the NF-κB pathway." (PMID 27754413, 2016).
infection (4 papers, 2017 to 2023). The state of being infected such as from the introduction of a foreign agent such as serum, vaccine, antigenic substance or organism. "This was also true for replication-defective adenoviral vectors, but the UBXN1 KO MEFs were equally or more susceptible to infection by adeno-associated virus vector, suggesting that the observed phenotype is not simply due to a general unhealthy or toxic cellular state." (PMID 28152074, 2017). "Here, we observed that TGEV infection led to increased UBXN1 expression levels during the late phase of infection in IPEC-J2 cells." (PMID 31029162, 2019). "We believe that the infection experiments using infectious NiV at biosafety level 4 would reveal the role of the potential ability of V protein to stabilize UBXN1 in the viral replication and pathogenesis in future." (PMID 29769705, 2018). "We hypothesized that UBXN1 might mediate the infection and replication of TGEV, thus controlling the expression of UBXN1, which might cause corresponding changes in TGEV." (PMID 31029162, 2019). "In addition, the analysis revealed that some of these proteins had been previously associated to SARS-CoV-2 early (FKBP2; UBXN1; PPP1R11), middle (UBXN1; PPP1R11; CAPN5) and late-stage infection in human male blood (FKBP2; UBXN1; PPP1R11; SURF4; SSU72)." (PMID 37063416, 2023). "After infection with TGEV, UBXN1 is induced to recruit MAVS." (PMID 31029162, 2019). "Finally, we confirmed by siRNA and overexpression assays that UBXN1 had a negative relationship with IFN-β, suggesting that TGEV infection promoted UBXN1 to inhibit the production of IFN-β in the late stage of infection to augment proliferation." (PMID 31029162, 2019).
UBXN1 also shares sentences with these, for which no sentence is quoted: colon adenocarcinoma (4 papers); cataract (1); gastric cancer (1); liver cancer (1); mantle cell lymphoma (1).